RPN1 (ribophorin I)
Description:
Subunit of the oligosaccharyl transferase (OST) complex that catalyzes the initial transfer of a defined glycan (Glc(3)Man(9)GlcNAc(2) in eukaryotes) from the lipid carrier dolichol-pyrophosphate to an asparagine residue within an Asn-X-Ser/Thr consensus motif in nascent polypeptide chains, the first step in protein N-glycosylation. N-glycosylation occurs cotranslationally and the complex associates with the Sec61 complex at the channel-forming translocon complex that mediates protein translocation across the endoplasmic reticulum (ER). All subunits are required for a maximal enzyme activity (By similarity).
Synonyms: OST1; RBPH1
Tractability: Small molecule: a structure with a bound ligand is known. Antibody: UniProt predicts a signal peptide or a membrane-spanning region. PROTAC: UniProt records ubiquitination sites on it; ubiquitination databases record sites on it; its protein half-life has been measured.
Gene: Protein-coding gene on chromosome 3 (128,619,968 to 128,681,075, reverse strand). Ensembl gene ENSG00000163902.
Subcellular location: Endoplasmic reticulum membrane; Melanosome
Subcellular location (Human Protein Atlas): Endoplasmic reticulum; Cytosol
Pathways (Reactome):
Disease: Maturation of DENV proteins; Maturation of spike protein
Metabolism of proteins: Asparagine N-linked glycosylation; SRP-dependent cotranslational protein targeting to membrane
Cell-Cell communication: Regulation of CDH1 posttranslational processing and trafficking to plasma membrane
Immune System: PD-L1(CD274) glycosylation and translocation to plasma membrane
Gene Ontology:
Molecular function: protein binding; RNA binding; dolichyl-diphosphooligosaccharide-protein glycotransferase activity
Biological process: protein N-linked glycosylation; glycoprotein biosynthetic process
Cellular component: cytosol; endoplasmic reticulum; melanosome; membrane; oligosaccharyltransferase complex; oligosaccharyltransferase complex A; oligosaccharyltransferase complex B; endoplasmic reticulum membrane; rough endoplasmic reticulum
Genetic constraint (gnomAD): Loss-of-function variants: 8 observed, 47.83 expected, observed/expected ratio (o/e) 0.17, 90% interval 0.097 to 0.3. The upper end of that interval is the gene's LOEUF score, 0.3, which puts it in group 1 of 6, group 1 being the genes least tolerant of losing a copy. Missense variants: 655 observed, 732.46 expected, observed/expected ratio (o/e) 0.89, 90% interval 0.84 to 0.95. Synonymous variants: 303 observed, 300.77 expected, observed/expected ratio (o/e) 1.01, 90% interval 0.92 to 1.11.
Homologues: Orthologues: chimpanzee RPN1 (99% identical), rabbit RPN1 (97% identical), dog RPN1 (96% identical), mouse Rpn1 (95% identical), pig RPN1 (95% identical), guinea pig RPN1 (95% identical), rat Rpn1 (95% identical), macaque RPN1 (93% identical), tropical clawed frog rpn1 (80% identical), zebrafish rpn1 (70% identical), Caenorhabditis elegans ribo-1 (39% identical), Drosophila melanogaster CG33303 (35% identical).
Diseases named in the same sentence as RPN1 in open-access papers:
RPN1 is named in the same sentence as 61 diseases in open-access papers, as found by Europe PMC text mining. Sharing a sentence is not in itself a finding about the gene and the disease. The quoted sentences say what the papers report.
breast carcinoma (13 papers, 2021 to 2025). "In vitro, the inhibition of RPN1 results in decreased proliferation and invasion of breast cancer cells, along with the induction of apoptosis caused by endoplasmic reticulum stress." (PMID 39993959, 2025). "Using the KMplotter online tool, high RPN1 expression was associated with poorer prognosis in patients with lung, colon, and breast cancers (HR > 1, P < 0.05)." (PMID 39749324, 2024). "RPN1 is upregulated in breast cancer and has also been associated with several other cancers, such as high-grade ovarian serous adenocarcinoma, colon adenocarcinoma, oesophageal adenocarcinoma, and bladder urothelial carcinoma." (PMID 36845707, 2023). "Studies have shown that endoplasmic reticulum stress-induced apoptosis inhibits the proliferation and invasion of breast cancer cells after RPN1 knockout." (PMID 41203639, 2025). "Compared with the normal human breast epithelial cell line MCF10A, there was also an increased tendency of RPN1 expression in breast cancer cell line MCF7." (PMID 38302629, 2024). "The RPN1 expression level was measured in breast cancer tissues and breast cancer cell lines (MCF7) using RT-qPCR." (PMID 38302629, 2024). "First, we performed qRT-PCR to monitor the RPN1 mRNA expression level in normal breast tissues and breast cancer tissues of patients." (PMID 38302629, 2024). "Biologically, our in vitro experiments clearly confirmed the high expression of RPN1 in the breast cancer cell line MCF7." (PMID 38302629, 2024). "Alterations in RPN1 expression or function have been observed in certain types of cancer, including breast cancer." (PMID 38302629, 2024). "In this study, we revealed that RPN1 promoted the proliferation and invasion of breast cancer cells by activating the PI3K/AKT/mTOR signaling pathway." (PMID 38302629, 2024). "Further, RPN1 knockdown inhibited the proliferation, migration, and invasion of breast cancer cells." (PMID 38302629, 2024). "In this study, we investigated the expression of RPN1 in breast cancer tissue and the role of RPN1 in proliferation, migration, and invasion of breast cancer cells." (PMID 38302629, 2024). "Taken together, RPN1 promotes the proliferation, migration, and invasion of breast cancer cells via the PI3K/AKT/mTOR signaling pathway." (PMID 38302629, 2024). "According to the qRT-PCR results, the RPN1 mRNA level was significantly increased in breast cancer tissues than that in normal breast tissues (n = 10, P < 0.05)." (PMID 38302629, 2024). "RPN1 plays a critical role in the process of N-glycosylation, and previous studies have shown that Rpn1 knockout in breast cancer cells could induce ERS, subsequently promoting apoptosis." (PMID 40083683, 2025). "Moreover, down-regulation of RPN1 inhibited the proliferation and invasion of breast cancer cells and triggered ER stress–induced apoptosis." (PMID 41203639, 2025). "Other breast cancer cell lines should be examined to confirm the expression and effect of RPN1." (PMID 38302629, 2024). "We found that RPN1 expression was up-regulated in breast cancer tissues and cells." (PMID 38302629, 2024). "Our study indicated that RPN1 played a vital role in the pathophysiology of breast cancer." (PMID 38302629, 2024). "Secondly, we did not explore the possibility of RPN1 to work as a diagnostic indicator for breast cancer." (PMID 38302629, 2024). "Considering that RPN1 and RPN2 belong to the same family of proteins, and that RPN2 functions in various tumors, we therefore hypothesized that RPN1 might be a carcinogenic gene in breast cancer." (PMID 38302629, 2024). "Our study results showed that RPN1 was overexpressed in breast cancer tissues and cells." (PMID 38302629, 2024). "In summary, RPN1 is clinically overexpressed in breast cancer tissues of patients." (PMID 38302629, 2024). "Although the detailed molecular mechanism is still unclear, it is apparent that RPN1 plays an important role in breast cancer and may be a potential therapeutic target for breast cancer." (PMID 38302629, 2024).
breast carcinoma (continued). "Furthermore, knockdown of RPN1 suppressed the proliferation and invasion of breast cancer cells in vitro and induced cell apoptosis triggered by endoplasmic reticulum stress." (PMID 34778038, 2021). "The protein expression level of RPN1 was also upregulated in breast cancer." (PMID 34778038, 2021). "Though it has been verified that the abnormal glycosylation is closely related to the development of breast cancer, the detail role of RPN1 in breast cancer remains unknown." (PMID 34778038, 2021). "Our results identified the oncogenic function of RPN1 in breast cancer, implying that RPN1 might be a potential biomarker and therapeutic target for breast cancer." (PMID 34778038, 2021). "Then, we focused on the function of RPN1 in breast cancer and its potential mechanisms." (PMID 34778038, 2021). "Therefore, we investigated how RPN1 affects the PI3K/AKT/mTOR signaling pathway in breast cancer." (PMID 38302629, 2024). "In addition, we examined the mechanism of RPN1 in the pathological development of breast cancer." (PMID 38302629, 2024). "Knockdown of RPN1 has been shown to reduce the proliferation and invasion of HCC cells and breast cancer cells." (PMID 41203639, 2025). "We also compared the RPN1 mRNA expression level in normal breast mammary epithelial cell line MCF10A and breast cancer cell line MCF7." (PMID 38302629, 2024). "Knockdown of RPN1-mediated aberrant protein hypoglycosylation can activate endoplasmic reticulum stress (ERS), thereby inhibiting the proliferation and invasion of breast cancer cells, promoting apoptosis, and suppressing tumor progression." (PMID 39749324, 2024). "The high expression of disulfidptosis genes (e.g., SLC3A2, RPN1, BRK1, ACTR2, ACTR3, SLC7A11, and NCKAP1) in the KM analysis of breast cancer indicated the poor prognosis of patients." (PMID 38035071, 2023). "Our study showed that the expression of several OST subunits including RPN1, RPN2, STT3A STT3B, and DDOST were upregulated in breast cancer samples." (PMID 34778038, 2021). "To investigate whether RPN1 functions in breast cancer pathogenesis through the activation of PI3K/AKT/mTOR signaling, we analyzed the impact of RPN1 on PI3K/AKT/mTOR signaling pathway activation." (PMID 38302629, 2024). "In the present study, we found that RPN1 was highly expressed in breast cancer tissues than it was in adjacent non-tumor tissues." (PMID 38302629, 2024). "We found that RPN1 level was up-regulated in breast cancer tissues and cells compared with adjacent non-tumor tissues or MCF10A cells." (PMID 38302629, 2024). "Abnormal RPN1/EVI1 fusion was also popular in myelodysplasia and acute myeloid leukemia and could be one of the relevant genes to predict breast cancer prognostic significance." (PMID 36072976, 2022). "RFS of the RPN1, RPN2, STT3A, STT3B, and DDOST with different molecular subtypes in breast cancer." (PMID 34778038, 2021). "Finally, although our results suggested that RPN1 promoted the proliferation and invasion of breast cancer cells by activating the PI3K/AKT/mTOR signaling pathway, the main target of RPN1 and the specific downstream signaling pathway of PI3K/AKT/mTOR require additional investigation." (PMID 38302629, 2024). "Recent studies have reported the involvement of RPN1 in pan-cancer, breast cancer, and glioma; however, these studies do not provide a comprehensive analysis of the clinical and biological significance of RPN1 and its potential regulatory mechanisms across different cancers." (PMID 39749324, 2024). "Overexpression of this gene at the protein level has also been detected in breast cancer by immunohistochemistry, with POMK being found both N-glycosylated (in a process regulated by ribophorin 1, or RPN1) and lacking N-glycosylation in both tumor and healthy tissues." (PMID 36494657, 2022).
glioma (8 papers, 2021 to 2025). A benign or malignant brain and spinal cord tumor that arises from glial cells (astrocytes, oligodendrocytes, ependymal cells). "Additionally, a study revealed that high expression of LRPPRC was positively correlated with a favorable prognosis for gliomas, but increased expression of RPN1 and GYS1 was associated with an unfavorable prognosis." (PMID 40109666, 2025). "Four of the IEAA-associated SNPs (rs2736100 in TERT, rs2275558 in PBX1, rs144317085 in TET2, and rs2492286 in RPN1) were associated with 16 unique traits including multiple cancers (e.g., lung cancer, glioma) and blood cell counts (e.g., platelet count, eosinophil count, red blood cell count)." (PMID 34187551, 2021). "Recently, the disulfidptosis related genes (DRGs) SLC3A2, NDUFA11, OXSM, NUBPL, LRPPRC, RPN1, and GYS1 were found to be significantly associated with glioma cells." (PMID 40109666, 2025). "Laboratory findings confirmed that RPN1 significantly promoted glioma cell proliferation and migration." (PMID 39993959, 2025). "In our study, we found that the expression of RPN1 increased in glioma cells and had significant effects on the proliferation and migration of glioma cells." (PMID 39993959, 2025). "Univariate Cox regression analysis has discerned significant associations between glioma patient survival trajectories and the expression profiles of several disulfidptosis-related genes, specifically SLC3A2, RPN1, NCKAP1, and SLC7A11 (all, P < 0.05)." (PMID 38977800, 2024). "Glioma tissues with increased GYS1 or RPN1 expression also exhibited elevated CD163 expression, aligning with our pan-cancer analysis findings." (PMID 38022537, 2023). "In our evaluation of the risk factors of eight genes, we identified SLC3A2, RPN1, NDUFA11, GYS1 and OXSM as potential risk factors for glioma prognosis." (PMID 38022537, 2023). "In glioma, RPN1, NDUFA11, and GYS1 were significantly positively correlated with StromalScore, ImmuneScore, and ESTIMATEScore." (PMID 38022537, 2023). "Additionally, wet lab experiments were conducted to validate the functional role of the key disulfidptosis gene RPN1, demonstrating its ability to promote glioma cell proliferation and migration." (PMID 39993959, 2025). "The TCGA glioma dataset was used to construct the risk model, and the risk score was calculated using the following formula: risk score = (− 0.3358 × LRPPRC expression) + (1.4536 × RPN1 expression) + (0.5002 × GYS1 expression)." (PMID 37864127, 2023). "The forest map shows that these five genes (SLC3A2, RPN1, NDUFA11, GYS1, OXSM) might be high-risk factors for glioma prognosis." (PMID 38022537, 2023). "However, the specific role of gene signature in glioma, including RPN1, has yet to be determined." (PMID 39993959, 2025). "GYS1, NDUFA11, OXSM, RPN1, and SLC3A2 play a role in promoting cancer in glioma, while LRPPRC, NCKAP1, NDUFS1, NUBPL and SLC7A11 play a role in inhibiting tumour." (PMID 39993959, 2025). "Spearman correlation analyses were employed to elucidate the interplay between SLC3A2, RPN1, NCKAP1, and SLC7A11 within the glioma landscape, revealing the strongest correlation between SLC3A2 and SLC7A11 (R = 0.242, P < 0.001)." (PMID 38977800, 2024). "We found a significant positive correlation between the expression of several DRGs (RPN1, GYS1) and StromalScore, ImmuneScore, and ESTIMATEScore in glioma." (PMID 38022537, 2023). "RPN1 and GYS1 were upregulated in glioma and were negatively correlated with favorable outcome, while LRPPRC1 was downregulated in glioma and positively correlated with favorable outcome." (PMID 37864127, 2023). "We explored their expression in dataset from TCGA and found that LRPPRC was downregulated, while RPN1 and GYS1 were upregulated in TCGA glioma dataset." (PMID 37864127, 2023). "We also examined RPN1, GYS1, and CD163 (M2 macrophage marker) expression levels in 83 glioma tissues." (PMID 38022537, 2023).
glioma (continued). "Additionally, a significant correlation was noted between the mesenchymal scores of low-grade gliomas in the brain and the expression of GYS1 and RPN1." (PMID 40295497, 2025).
bladder cancer (4 papers, 2022 to 2025). "Regarding RPN1, few studies have shown that inhibiting its expression can help design multiple drug combinations to treat bladder cancer." (PMID 37152941, 2023). "Other independent studies have highlighted the role of RPN1, HSPA5, and YIF1B as prognostic markers of the disease along with other sets of genes in bladder cancer." (PMID 40026699, 2025). "Our study has identified four disulfidptosis suppressor genes, namely SLC7A11, SLC3A2, RPN1, and NCKAP1, which play significant roles in the development and immune infiltration of bladder cancer." (PMID 37152941, 2023).
colorectal cancer (3 papers, 2019 to 2022). A primary or metastatic malignant neoplasm that affects the colon or rectum. "Consistently, SIGIRR localized predominantly to the cytoplasm and colocalized with RPN1 in the colorectal cancer tissues while it is primarily distributed along the basal lateral membrane in normal colonic epithelial cells." (PMID 35900274, 2022). "In total, 31 unique genes are included in the panels, plus we added the RPN1 gene, which was identified by us earlier as a reliable RG for lung, kidney, and colorectal cancers." (PMID 30881377, 2019). "According to Bestkeeper software version 1, the most stable and suitable housekeeping genes across our colorectal cancer samples are GAPDH 2 (HGK 1) with standard deviation 0.71 and p = 0.01, PUM1 2 (HGK 2), and RPN1 (HGK 3) are equally good and have the same standard deviations 0.94 and p=0.001." (PMID 33457124, 2020).
bladder urothelial carcinoma (2 papers, 2023 to 2024). "In addition, a group of disulfidptosis-related genes (GYS1, LRPPRC, NDUFA11, OXSM, RPN1, SLC3A2, and SLC7A1) are found to influence the prognosis of bladder urothelial carcinoma via immune cell infiltration." (PMID 39701955, 2024).
esophageal cancer (2 papers, 2019 to 2025). A primary or metastatic malignant neoplasm involving the esophagus. "According to the TCGA database, RPN1 exhibited significantly higher mRNA levels in esophageal cancer, including EAC and ESCC, compared to normal esophageal tissues." (PMID 41203639, 2025). "In addition, we found that Ribophorin I (RPN1) was also overexpressed in esophageal cancer samples, and exploring the effect of RPN1 on the occurrence and development of esophageal cancer cells and its molecular mechanism will be the focus of our work." (PMID 30940778, 2019). "In addition, the underlying mechanism by which RPN1 and RPN2 regulates the progression of esophageal cancer is still not well known." (PMID 30940778, 2019). "Subsequently, proteomic data from 124 EC patients were used to analyze the relationship between RPN1 and SEC22B protein expression and the prognosis of esophageal cancer." (PMID 41203639, 2025). "We explored the expression of RPN1 and SEC22B in esophageal cancer." (PMID 41203639, 2025).
gastric cancer (2 papers, 2021 to 2024). A primary or metastatic malignant neoplasm involving the stomach. "CCK-8 assays demonstrated that knockdown of RPN1 significantly reduced the proliferative capacity of lung cancer cells A549, gastric cancer cells MGC-803, and colon cancer cells SW480." (PMID 39749324, 2024).
lung adenocarcinoma (2 papers, 2023 to 2024). A carcinoma that arises from the lung and is characterized by the presence of malignant glandular epithelial cells. "According to the findings, lung squamous cell carcinoma and lung adenocarcinoma cells have higher levels of RAC1, RPN1, and SLC7A11 mRNA than normal lung epithelial cells." (PMID 38968580, 2024).
prostate carcinoma (2 papers, 2019 to 2025). A carcinoma that arises from epithelial cells of the prostate gland. "RPN1 gene suggested by us demonstrated high expression stability score in lung, renal, colon, liver, thyroid, and prostate cancers." (PMID 30881377, 2019). "Building on our previous research, further analysis of tumor progression within the training set revealed that RPN1 may act as a suppressor of prostate cancer progression, while OXSM, NDUFA11, and SLC7A11 appear to promote disease progression." (PMID 41330917, 2025). "Among them, SLC7A11, OXSM, RPN1, and NDUFA11 showed higher expression levels in prostate cancer tissues compared to normal samples." (PMID 41330917, 2025).